IGF2BP2 (insulin like growth factor 2 mRNA binding protein 2)
Diseases named in the same sentence as IGF2BP2 in open-access papers (continued):
Sharing a sentence is not in itself a finding about the gene and the disease.
cancer (continued). "We next investigated the role of IGF2BP2 as a therapeutic cancer target." (PMID 40347943, 2025). "In most cancers analyzed, IGF2BP2 mRNA was frequently overexpressed." (PMID 40141058, 2025). "The enhanced mRNA stability leads to persistent AR‐V7 expression inside cells, thereby contributing to CRPC progression and enzalutamide resistance, in line with previous studies demonstrating the role of IGF2BP2 in regulating cancer progression by stabilizing various mRNA and lncRNA transcripts." (PMID 39948708, 2025). "In addition, these APA genes following METTL3 and IGF2BP2 knockdown were enriched in several cancer‐related pathways, such as the Hippo pathway, autophagy, the TGF‐beta pathway, the AMPK pathway and cancers." (PMID 40629911, 2025). "While the precise role of IGF2BP2 in ferroptosis remains unclear, it is known that lncRNAs play a significant role in cancer progression." (PMID 40271153, 2025). "circHIPK3 contains multiple sites for the same RBPs (e.g., DDX54, EIF4A3, FMR1, IGF2BP1, IGF2BP2, LIN28B and MOV10), many of which are involved in chemoresistance and organelle-like structures, such as Cajal body and P-body which are associated with cancer." (PMID 40061896, 2025). "Nevertheless, more studies are needed to explore whether other m6A-related genes are associated with the radiosensitivity of HCC and whether METTL3/IGF2BP2 can predict the radiosensitivity of pan-cancer." (PMID 39799112, 2025). "This regulatory capacity underscores the importance of KH domains in controlling cellular processes, and their dysregulation could have profound implications for diseases such as cancer, where IGF2BP2 plays a role in oncogenic mRNA stabilization." (PMID 39596216, 2024). "Although the role of IGF2BP2 in cancer has been extensively studied, the mechanism by which it regulates cell proliferation and differentiation remains unclear." (PMID 38443392, 2024). "The m6A reader IGF2BP2 could regulate DANCR to promote cancer stemness-like properties and pathogenesis." (PMID 38229597, 2024). "A deeper understanding of IGF2BP2’s mechanisms in cancer could offer new perspectives and strategies for achieving optimal treatment outcomes." (PMID 39596216, 2024). "IGF2BP2 mRNA levels were correlated with cancer immunity in both LUSC and LUAD patients." (PMID 38867248, 2024). "Importantly, IGF2BP2 recruitment has been shown to promote mRNA stability, which in turn promotes M2 macrophage polarization to accelerate cancer malignant progression." (PMID 39014364, 2024). "As we navigate the intricate balance between autophagy and cell survival, modulating IGF2BP2 activity could emerge as an avenue for influencing cancer cell behavior." (PMID 38682020, 2024). "Furthermore, the interaction between IGF2BP2 and several lncRNAs and miRNAs in cancer cells has been studied by multiple research groups." (PMID 38328550, 2024). "IGF2BP2 is highly expressed in certain cancer types and promotes cancer progression." (PMID 38328550, 2024). "IGF2BP2 has been identified as having oncogenic roles in human cancers." (PMID 39731162, 2024). "Identifying molecules that can specifically inhibit IGF2BP2’s RNA-binding ability could offer more effective therapeutic strategies for treating cancers." (PMID 39596216, 2024). "Modulating IGF2BP2 activity could potentially impact cancer cell behavior and open avenues for developing novel treatment strategies." (PMID 38682020, 2024). "By targeting IGF2BP2, it may be possible to disrupt these cancer-promoting pathways, enhancing the effectiveness of chemotherapy, immunotherapy, and metabolic inhibitors." (PMID 39596216, 2024). "Xu revealed the oncogenic role of IGF2BP2 in PC and could promote cancer proliferation by activating the PI3K/Akt signaling pathway." (PMID 35908253, 2023). "Accumulating evidence links IGF2BP2 overexpression with cancer initiation and progression." (PMID 37936610, 2023).
cancer (continued). "Combination therapy of chemo drugs or targeting drugs with inhibitors or nucleic acid drugs targeting the IGF2BP2/AC026356.1 loop in vivo may further help in identifying novel therapeutic sensitizers for multiple regimens of cancer treatment." (PMID 37142269, 2023). "This might be due to the fact that IGF2BP1 and IGF2BP3 are oncofetal proteins that are not expressed in most adult tissues but often reactivated in cancer, whereas IGF2BP2 expression is retained throughout adulthood." (PMID 37503349, 2023). "LINRIS can induce the K139 ubiquitination of IGF2BP2, thus preventing the degradation of IGF2BP2 by lysosomes, which keeps the content of IGF2BP2 protein at a certain level, and promotes the glycolysis and proliferation of cancer cells through the IGF2BP2/MYC/glycolysis axis." (PMID 37582735, 2023). "It is well known that m6A modification induces oncogenic protein expression, cancer cell proliferation, survival, tumorigenesis and progression, and thus the overexpression of m6A modification reader (IGF2BP2) is highly likely to promote the progression of LUAD." (PMID 37353784, 2023). "Furthermore, we identify gene fusions, including an experimentally validated IGF2BP2::TESPA1 fusion, which is misclassified as high TESPA1 expression in matched short-read data, and call mutations confirmed by targeted NGS cancer gene panel results." (PMID 38012143, 2023). "Furthermore, in vivo studies using Igf2bp2 knockout mice showed that IGF2BP2 serves as an important regulator driving the progression of malignant tumors." (PMID 37936610, 2023). "IGF2BP2 is up-regulated in a variety of tumors, and its biological activity contributes to cancer formation by interacting with various non-coding RNAs including microRNAs (miRNAs), long non-coding RNAs (lncRNAs), and circular RNAs (circRNAs) (Wang, Chen & Qiang, 2021)." (PMID 38025760, 2023). "IGF2BP2 also relates to several cancers, including liver, pancreatic, breast, and so on." (PMID 36772473, 2023). "IGF2BP2 is a member of the conserved oncofetal RNA-binding protein family that acts as a N6-methyladenosine (m6A) reader, and it is involved in the development and progression of various cancer types." (PMID 36289466, 2022). "Our study showed a general unfavorable role of IGF2BP2 in cancers, which might have a broad application among cancers and deserves further study." (PMID 36281789, 2022). "To investigate whether IGF2BP2 has broad value, we conducted further studies on IGF2BP2 across all cancers." (PMID 36281789, 2022). "In other cancer types, IGF2BP2 had also been found to play a carcinogenic effect." (PMID 36281789, 2022). "In turn, IGF2BP2 also directly stabilizes noncoding RNAs to promote cancer progression." (PMID 35541906, 2022). "This signifies that IGF2BP2 exerts a cancer-promoting influence on CRC." (PMID 35014946, 2022). "In addition to cancer, IGF2BP2-mediated m6A modification also plays crucial roles in other physiological and pathological contexts." (PMID 35541906, 2022). "As IGF2BP2 and HuR exert cancer-promoting effects in tumorigenesis, we speculated that circEIF3H might coordinately interact with IGF2BP2/HuR and served as a molecular scaffold." (PMID 35568705, 2022). "The expression of IGF2BP2 in OSCC cancer tissue was examined via IHC staining." (PMID 35919812, 2022). "Previous studies have shown that IGF2BP2 is frequently dysregulated in multiple human cancers." (PMID 36257938, 2022). "Based on the GSEA results, IGF2BP2 might promote the malignant progression of OSCC by affecting cancer-related and immune-related biological functions and pathways." (PMID 35299748, 2022). "In addition, G3BP2, WTAP, PCIF1, HNRNPA2B1, EIF3A, and IGF2BP2 were modulated in ≥three cancer types in uncertain manners." (PMID 35211628, 2022). "Accumulating evidence highlights the significance of IGF2BP2 as a key regulator of cancer." (PMID 35002727, 2021).
cancer (continued). "Overall, we speculate the complex relationship among IGF2BP2, circRNAs, miRNAs and lncRNAs participates in the development of both metabolic diseases and cancers." (PMID 33568150, 2021). "Bind with IGF2BP2 to stabilize c-Myc, thus promoting the cancer cell proliferation and viability." (PMID 34888249, 2021). "Emerging evidence shows that IGF2BP2 is an N6-methyladenosine (m6A) reader that participates in the development and progression of cancers by communicating with different RNAs such as microRNAs (miRNAs), messenger RNAs (mRNAs) and long non-coding RNAs (lncRNAs)." (PMID 33568150, 2021). "Moreover, in the same study, the authors have shown that DDX11-AS1 is specifically bound by the insulin-like growth factor 2 mRNA-binding protein 2 (IGF2BP2), an RNA-binding protein that plays an oncogenic role in many cancers." (PMID 33802088, 2021). "Next, we determined whether IGF2BP2 can regulate expression of lncRNAs because lncRNAs have been shown to function as master gene regulators and play an important role in cancer initiation, progression, and metastasis as well as stem cell maintenance." (PMID 31804607, 2020). "However, our results suggest that lncRNA DANCR is a novel target for IGF2BP2 through m6A modification in PC, and that it promotes cancer stemness-like properties and PC pathogenesis." (PMID 32754191, 2020). "Thus, IGF2BP2 was found to be a positive regulator of cancer growth." (PMID 40448344, 2025). "However, there is limited research on the roles of YTHDF3 and IGF2BP2 in ferroptosis and cancer, and further investigation is necessary to determine whether these proteins contribute to ferroptosis regulation." (PMID 40271153, 2025). "Based on the previous studies identifying the role of IGF2BP2 in various cancer types and our analysis of both primary prostate and CRPC patient samples, we postulated that the upregulation of IGF2BP2 might be linked to CRPC progression and enzalutamide resistance." (PMID 39948708, 2025). "Therefore, further in-depth investigation into this mechanism is warranted, as it could provide a more comprehensive understanding of the role of IGF2BP2 in cancer." (PMID 39596216, 2024). "Notably, the IGF2BP2 SNP is associated with both T2DM and cancer." (PMID 39659616, 2024). "Research into IGF2BP2’s interactions and regulatory networks is crucial, as it may reveal additional targets for intervention, ultimately leading to improved therapeutic strategies and outcomes for patients with cancer." (PMID 39596216, 2024). "However, the fundamental mechanism through which IGF2BP2 promotes cancer cell survival, proliferation, and migration is yet unknown." (PMID 37828232, 2023). "Importantly, IGF2BP2 also acts as an inhibitor in many cancers." (PMID 33952279, 2021). "Additionally, IGF2BP2 is an independent prognostic factor for multiple cancer types." (PMID 33568150, 2021). "Moreover, accumulating evidence supports the role of IGF2BP2 in cancer." (PMID 34809621, 2021). "GO enrichment analysis shows these genes belong to categories that may relate to IGF2BP2 involvement in cancer invasion and metastasis, including cell-substrate adhesion, spreading, and wound healing, as well as the canonical function for IGF2BP2 pathway, cellular glucose homeostasis." (PMID 31484926, 2019). "Furthermore, studies from independent laboratories suggest that IGF2BP2 participates in the maintenance of cancer stem cells (CSCs), implicating that IGF2BP2 may be important for the chemoresistance and recurrence of the diseases." (PMID 29736175, 2018). "Functionally, IGF2BP2 promotes proliferation, suppresses thyroid differentiation genes (TSHR, SLC26A4, SLC5A5, TPO, PAX8, FOXE1, and NKX2.1), and enhances cancer stemness." (PMID 41522349, 2026). "The m6A reader, IGF2BP2, has been shown to be upregulated in pancreatic cancer and increases the expression of mML DANCR, which promotes proliferation and cancer stemness." (PMID 40243425, 2025).
cancer (continued). "Using the four-gene signature (YTHDF3, RBM15B, IGF2BP2, and TRMT61A), we constructed a nomogram to estimate 1-year and 3-year overall survival probabilities in patients from the eight selected TCGA cancer types." (PMID 40565233, 2025). "This was rescued to some extent with overexpression of IGF2BP2, indicating a role for LINRIS-IGF2BP2-MYC in glycolysis and cancer proliferation." (PMID 40126351, 2025). "We further confirmed this classification by calculating the average expression of IGF2BP1, IGF2BP2, and IGF2BP3 across cancer types and clusters, which consistently showed the highest levels in IGF2BP-H, intermediate in IGF2BP-M, and lowest in IGF2BP-L." (PMID 41049442, 2025). "IGF2BP2 belongs to the family of IGF2 RBPs, which are critical regulators of growth and development in various cancer types." (PMID 39948708, 2025). "The current findings build upon this by revealing the interplay between ZFAS1, IGF2BP2, and STAT3, which appears to be an important mechanism driving cancer progression." (PMID 40697388, 2025). "Further analysis of cancer-related genes showed that TPA and mezerein exposure upregulates several oncogenes, including Hmga1, Foxm1, Igf2bp2, Anln, Ezh2, and Suz12." (PMID 40182023, 2025). "When LINC00901 is upregulated, IGF2BP2 is also upregulated, stabilizing MYC mRNA, which in turn upregulates MYC and promotes cancer progression." (PMID 40448344, 2025). "IGF2BP1, IGF2BP2, and IGF2BP3 were upregulated in the SCAN-B cohort, aligning with their widespread dysregulation in cancer." (PMID 40918643, 2025). "Polo‐like kinase 1 (PLK1) mRNA is modified by m6A and stabilized by binding to IGF2BP2, which increases PLK1 expression and contributes to cancer progression." (PMID 40448344, 2025). "HPV 16/18 E6/E7 activates IGF2BP2 and regulates MYC methylation to facilitate aerobic glycolysis and cancer progression in CC." (PMID 38721006, 2024). "IGF2BP2, IGF2BP3, RBM15, WTAP, and YTHDC2 are positively correlated to the immune score in a few cancer types." (PMID 39457524, 2024). "Previous studies have demonstrated the critical role of M6A regulators FTO, IGF2BP2 and IGF2BP3 in ovarian and other cancers." (PMID 38714753, 2024). "This stabilization prevents IGF2BP2 degradation via the autophagy‐lysosome pathway, facilitating MYC‐driven glycolysis in cancer cells." (PMID 39377984, 2024). "This study aimed to investigate the interaction between HULC and insulin-like growth factor 2 mRNA-binding protein 2 (IGF2BP2) in CRC and its role in promoting cancer progression." (PMID 39668820, 2024). "Insulin‐like growth factor 2 mRNA‐binding protein 2 (IGF2BP2) is a widely studied RBP, and sirtuin 1 also known as SIRT1 has been reported to be involved in cancer progression." (PMID 36510377, 2023). "IGF2BP2 knockdown in TU686 and FD-LSC-1 cell lines remarkably suppressed cancer cell viability, colony formation capacity, and cell invasion and elicited G0/1-phase arrest of cell cycle." (PMID 37816718, 2023). "IGF2BP2 has the ability to stabilize HMGA1 mRNA and RAF196 mRNA, thereby enhancing cancer cell viability and promoting cancer cell proliferation." (PMID 37631029, 2023). "Abnormal expression of IGF2BP2 and reactivation of IGF2BP1 and 3 are often seen during cancer progression." (PMID 37503349, 2023). "In this study, through promoting CDK6 mRNA stability, IGF2BP2 increased CDK6 and p-Rb levels, therefore relieving the cell cycle arrest in G0/1 phase and promoting cancer cell proliferation." (PMID 37816718, 2023). "IGF2BP2, an RNA binding protein (RBP), was recognized recently as a member of unique class of m6A readers that play oncogenic roles in cancers." (PMID 37936610, 2023).
cancer (continued). "To understand the expression and prognosis of ANO1 and IGF2BP2 across cancers, we used the GEPIA2 web server to analyze data containing 33 cancer subtypes derived from TCGA and GTEx databases." (PMID 35299748, 2022). "mir-1193 has been found to inhibit the proliferation and invasion of cancer cells by directly acting on transmembrane 9 superfamily member 3 (TM9SF3) and insulin-like growth factor 2 mRNA binding protein 2 (IGF2BP2)." (PMID 35937294, 2022). "The result shown that the expression of both protein and RNA levels of IGF2BP2 and IGF2BP3 were up-regulated in COAD, ESCA, and STAD cancer tissues compared with paracancerous." (PMID 36686749, 2022). "According to the GSEA results, high expression of IGF2BP2 mainly activates the EMT, glycolysis, and cell cycle three cancer-related pathways that affect cancer cell proliferation, migration, and invasion." (PMID 35299748, 2022). "Immunofluorescence staining and qRT-PCR analyses also showed that the expression of IGF2BP2 and IGF2BP3 were higher in cancer tissues than that in adjacent normal tissues." (PMID 36686749, 2022). "Previous studies have shown that, among these genes, CTLA4, IGF2BP2, and TNFRSF4 are involved in cancer procession and affect the prognosis of patients with OSCC." (PMID 36185403, 2022). "lncRNA LINRIS stabilizes IGF2BP2 to boost the aerobic glycolysis of CRC cells, hence facilitating the evolvement of the cancer." (PMID 35014946, 2022). "Dysregulated IGF2BP2 expression leads to the accumulation of oncogenic molecules, such as MYC, thus supporting the malignant state of cancer cells." (PMID 35002506, 2022). "Expression of IGF2BP2 has also been shown to be up-regulated in colorectal cancer (CRC) tissues, promoting proliferation and survival of the cancer cells." (PMID 33568150, 2021). "IGF2BP2 regulates the m6A-modified lncRNA DANCR to promote cancer stemness-like properties and cancer pathogenesis." (PMID 34692544, 2021). "IGF2BP2 and lncRNA DANCR have been reported to interact and promote the cancer stemness-like properties of pancreatic cancer." (PMID 35004679, 2021). "In thyroid cancer, lncRNA MALAT1 competitively binds to miR-204, upregulates IGF2BP2 and enhances MYC expression in m6A-dependent manner, conferring a stimulatory effect on cancer progression." (PMID 35004679, 2021). "METTL3 acts on the reader IGF2BP2, and IGF2BP2 directly binds to a specific m6A site of in SOX2 CDS and controls the half-life of SOX2 mRNA by relying on m6A modification to produce cancer-promoting effects." (PMID 34246319, 2021). "By searching the GSCALite database, we found that the expressions of many m6A methylation regulators (especially IGF2BP1, IGF2BP2, and IGF2BP3) were changed across multiple cancer types." (PMID 35003212, 2021). "The expression of the IGF2BP2 gene in pan-cancer was examined with TIMER, and we verified the expression and prognostic value of the IGF2BP2 gene in HNSCC using GEPIA2." (PMID 33816266, 2021). "Except for HMGA2, IGF2BP2 markedly promotes functions of IGF and proliferation of cancer cells by binding and stabilizing HMGA1." (PMID 33568150, 2021). "IGF2BP2 is highly expressed in PAC and interacts with lncRNA DANCR, leading to an increase in its stability and promoting cancer cell proliferation." (PMID 32911345, 2020). "The experiments further demonstrate that IGF2BP2 can stabilize lncRNA-DANCR by enhancing m6A modification to stabilize DANCR RNA, thus promoting cancer cell proliferation." (PMID 33552994, 2020). "It has also been reported that IGF2BP2 regulates lncRNA DANCR through m6A modification, and IGF2BP2 and DANCR jointly promote the stemness-like characteristics of cancer and the pathogenesis of PC." (PMID 32754191, 2020). "MiR-1193 was previously shown to suppress proliferation and invasion of cancer cells through directly targeting transmembrane 9 superfamily member 3 (TM9SF3), and insulin-like growth factor 2 mRNA binding protein 2 (IGF2BP2)." (PMID 33046105, 2020).